NBPF5P (NBPF member 5, pseudogene)
Synonyms: formerly NBPF5
Gene: Transcribed unprocessed pseudogene on chromosome 1 (108,376,119 to 108,385,897, forward strand). Ensembl gene ENSG00000243967.
Subcellular location: Cytoplasm